NOTCH1 (notch receptor 1)
Diseases named in the same sentence as NOTCH1 in open-access papers (continued):
Sharing a sentence is not in itself a finding about the gene and the disease.
head and neck cancer (23 papers, 2012 to 2026). A primary or metastatic malignant neoplasm affecting the head and neck. "In head and neck cancer, the Fs mutations, including those in NOTCH1, were found to be enriched in responders to anti-PD-1/PD-L1 therapies." (PMID 39451738, 2024). "High levels of Notch1 correlates to higher numbers of tumor-associated macrophages (TAMs) in head and neck cancer and NOTCH1 and NOTCH2 induce a TAM-anti-inflammatory phenotype via JAG1." (PMID 32796631, 2020). "There are some variations by tumor site, such as NOTCH1 mutations which are primarily found in head and neck cancers." (PMID 28771191, 2017). "Interestingly, there was an enriched rate of response to WNT974 among head and neck cancer cell lines with Notch1 loss-of-function (LOF) mutations." (PMID 27117272, 2016). "Research studies validate the role of NOTCH1 in tumor cell proliferation and immune evasion mechanisms in head and neck cancers while demonstrating that increased expression levels are predicted at higher stages and have poor clinical outcomes." (PMID 40672020, 2025). "After analyzing the overexpression of TRPM7, NFATC3, and Notch1 within different head and neck cancer cell lines, we screened cell lines suitable for subsequent experiments." (PMID 35771152, 2022). "Young-onset head and neck cancer patients with FAT1 germline variants had a shorter overall survival; therefore, restoration of the functional NOTCH1 or FAT1 expression in nonsense mutation NOTCH1 or FAT1 in HSNCC is a key issue in anticancer therapy." (PMID 36428516, 2022). "NOTCH1 and Notch pathway are generally regarded as having a tumor suppressor function in head and neck cancer which hampers the possibility to use γ-secretase inhibitors that are in development for cancers with Notch pathway activation." (PMID 35664801, 2022). "First, we checked for the presence of Notch pathway transcript expression by real-time PCR and western analysis of NOTCH1 protein using multiple head and neck cancers cell lines (NT8e, AW13516, CAL27 and DOK)." (PMID 27391340, 2016). "However, other mutations, such as Notch1, CDKN2A, FAT1, PTEN HRAS, and PI3KCA, frequently occurring in head and neck cancer, may influence metastatic events." (PMID 37894373, 2023). "In this study, we demonstrated that EGCG suppresses Notch1 and cleaved Notch1 in 5FUR cell lines indicating that EGCG treatment can inhibit the Notch signaling pathway in CRC - a finding that is consistent with a previous study conducted in head and neck cancer." (PMID 26930714, 2016). "This is also supported by the early in vitro study of WNT974, which revealed an enriched rate of response to WNT974 among head and neck cancer cell lines with Notch1 loss-of-function (LOF) mutations, suggesting that Notch1 mutation status may play a role in responsiveness to Wnt pathway inhibition." (PMID 27117272, 2016). "Data retrieved from TCGA head neck cancer dataset suggested that DNA copy number of HES1, a putative downstream target of NOTCH1, significantly increased in human HNSCC than in its control counterpart (P = 1.06E-51)." (PMID 27108536, 2016).
myocardial infarction (23 papers, 2013 to 2025). Gross necrosis of the myocardium, as a result of interruption of the blood supply to the area, as in coronary thrombosis. "Research demonstrated that Notch1 signaling provides protective effects against conditions such as cardiomyopathy, myocardial infarction, pathological cardiac enlargement, and damage caused by ischemia-reperfusion." (PMID 39568588, 2024). "Inhibition of AMPK signaling by Notch1 enhances cardiac dysfunction caused by myocardial infarction." (PMID 33879068, 2021). "Notch1-deficient mice show more severe myocardial infarction (MI) and have unfavorable cardiac parameters as compared to wild-type mice." (PMID 34945766, 2021). "Conversely, in systemic Notch1 deficient mice, I/R leads to the development of a larger myocardial infarct area and worsening of heart function than wild-type controls." (PMID 28424623, 2017). "NOTCH1 is also associated with the development of myocardial infarction (MI)." (PMID 37628760, 2023). "EVs secreted by Notch1-overexpressing C-MSCs caneffectively prevent cell death after myocardial infarction, promote angiogenesisand CM proliferation, and restore cardiac function." (PMID 40160574, 2025). "Here, the association between Notch1 and acute myocardial infarction (AMI) was investigated using proteomics, to assess the possibility of using Notch1 as a biomarker for the disease." (PMID 38841263, 2024). "After treatment, mouse heart function, myocardial injury markers, myocardial infarction and Notch1/Hes1 expression, endoplasmic reticulum stress markers, and apoptosis-related proteins were determined." (PMID 35588098, 2022). "Myocardial Notch1 level is activated after injury and enhances the anti-apoptotic signaling Akt and Bcl-2 and improves heart function after myocardial infarction." (PMID 36036015, 2022). "We previously reported that Notch1 can reduce mitochondrial lysis, reduce myocardial infarct size, and inhibit ventricular remodeling." (PMID 36611931, 2022). "Jagged1 and Notch1 are expressed in the adult heart and protect heart tissue against cardiomyopathy, myocardial infarction, pathological hypertrophy, and I-R injury." (PMID 36036015, 2022). "We also reported that Notch1 can reduce mitochondrial lysis, reduce myocardial infarct size, and inhibit ventricular remodeling." (PMID 36611931, 2022). "In a mice myocardial infarction (MI) model, it was demonstrated that silencing of the miR-34 family suppresses Notch1, resulting in weakened MI-induced pathological left ventricular remodeling and improved cardiac function with increased angiogenesis." (PMID 34677194, 2021). "Other researchers also reported that acupoint gel embedding could significantly diminish myocardial infarction size and inflammatory responses via the Notch-1 signaling pathway." (PMID 35656078, 2022). "Notch1 signaling has been reported to be important for proper myocardial function and response to injury, especially in myocardial ischemia I/R injury, myocardial infarction, and cardiac hypertrophy." (PMID 34504645, 2021). "In summary, hydrogels offer an additional platform for the 3D culture of cardiovascular cells for exploring the possibilities in regeneration on myocardial infarction via the activations of Notch1–Dll1 and Notch1–Jag1 receptor–ligand bindings in the CMs and CPCs." (PMID 34677194, 2021). "Jagged1 and Notch1 are expressed in the adult heart, and these proteins protect cardiac tissue under various pathophysiological conditions, including alcoholic cardiomyopathy, myocardial infarction, cardiac hypertrophy, and ischemia-reperfusion injury." (PMID 27057278, 2016). "a DLBCL mouse model was created by lentivirus-mediated knockdown of NOTCH1 and EZH2 genes, followed by myocardial infarction induction." (PMID 39951437, 2025). "In this study, NOTCH1 was found to suppress EZH2 gene expression, impacting DLBCL tumorigenicity and myocardial infarction extent." (PMID 39951437, 2025).
myocardial infarction (continued). "The study revealed an increase in Notch1 and DLL4 levels, particularly at the 24th hr and 7th day after the occurrence of myocardial infarction." (PMID 39850112, 2025). "NOTCH1 signaling influences DLBCL development and myocardial infarction severity through the EZH2/STAT3 pathway, leading to increased heart fibrosis." (PMID 39951437, 2025). "Also, YQHX was reported to ameliorate the cardiac energy metabolism via cross-talk between the LKB1-dependent Notch1 and AMPK after myocardial infarction." (PMID 30223807, 2018). "YQHX could ameliorate the cardiac energy metabolism via cross-talk between the LKB1-dependent Notch1 and AMPK after myocardial infarction." (PMID 30223807, 2018). "We aim to investigate the exacerbation of cardiac fibrosis by studying the effects of the NOTCH1 signaling pathway through EZH2-induced excessive methylation, resulting in the production of GM-CSF and IL-6, while establishing an animal model of DLBCL with an additional myocardial infarction model." (PMID 39951437, 2025).
multiple myeloma (22 papers, 2013 to 2024). "In ex vivo and in vivo knockdown studies, interactions between Jagged1/2 and Notch1/2 have been demonstrated to promote adhesion, migration, and organization of multiple myeloma endothelial cells (MMECs)." (PMID 39619207, 2024). "The majority of multiple myeloma (MM) cases (92%) overexpress Notch1 and Jagged1 and expression of these genes correlate with disease progression." (PMID 39619207, 2024). "Hyperactivation of Notch ligands in myeloma cells (Jagged1/2) activates Notch transmembrane receptors in MSCs and osteoprogenitors (i.e., Notch 1)." (PMID 34067236, 2021). "Mir-27 negatively targets the ubiquitin ligase NEDD4, which specifically binds Notch1 to increase the ubiquitination of Notch1 in multiple myeloma cells." (PMID 34769343, 2021). "Notch1 signaling has been shown to play a role in CCL19-driven homing of CLL cells and Notch1 signaling inhibition in multiple myeloma was described to prevent tumor cell migration." (PMID 31676012, 2019). "Other studies have described the involvement of Notch1 and Jagged1 in microenvironment-mediated chemoresistance: indeed, the inhibition of Notch1 up-regulation in multiple myeloma is sufficient to abrogate hBM-MSC-induced chemoresistance." (PMID 26967055, 2016). "In addition, in the multiple myeloma setting a direct positive control of CXCR4 by NOTCH1 has been recently proposed." (PMID 28938632, 2017). "In myeloma and other malignant lymphoid cell lines, studies have demonstrated that Notch1 is closely related to bone marrow stroma–mediated drug resistance, and that inhibition of Notch signalling sensitizes cells to chemotherapy and prevents bone marrow-mediated chemoresistance." (PMID 23289374, 2013). "For example, NOTCH1 inhibition in MM induces apoptosis and reduces the proliferation rate, and the knockdown of DICER significantly decreased growth and viability of myeloma cells." (PMID 35361260, 2022). "In multiple myeloma cells, NEDD4 binds specifically to the Notch1 protein and increases its ubiquitination and degradation." (PMID 35355403, 2022). "mir-27 or Notch1 overexpression or NEDD4 silencing diminished autophagy but enhanced proliferation and invasion of multiple myeloma cells." (PMID 34769343, 2021). "Collectively, mir-27 elevated Notch1 expression by targeting NEDD4 and promoted the development of multiple myeloma by inhibiting cell autophagy, thus providing a scientific basis for innovative treatment of multiple myeloma." (PMID 34769343, 2021). "Similarly, in multiple myelomas, Notch1, Notch2, and JAG1 were highly expressed in primary tumor samples, and JAG1-induced Notch activation drove myeloma cell proliferation." (PMID 25309874, 2014).
oral cancer (22 papers, 2013 to 2025). "The similar frequency of NOTCH1 driver mutations in oral cancer and normal oral epithelium suggests that NOTCH1 mutations lead to benign clonal expansions at similar risk of transformation than NOTCH1-wild-type cells." (PMID 41062696, 2025). "Some authors have described an association of the strong immunoexpression of Notch1 with advanced clinical stage and/or with lymph node metastasis in patients with oral cancer." (PMID 33854547, 2021). "The common Notch1 mutations reported in oral cancer are missense that occur on or near the ligand binding domain (EGF repeats) or the ankyrin domains." (PMID 35047986, 2020). "A study discovered that Cur could decrease oral carcinoma CAL-27 cells viability owing to the apoptotic activation associated with Notch-1 and NF-κB downregulation." (PMID 36641489, 2023). "Moreover, constitutively phosphoryl-mimicking mutation of FADD also enhances Notch-1 signaling in muscle regeneration through promoting ERK phosphorylation is consistent with our finding in oral cancer cells." (PMID 35249111, 2022). "However, relative to the prognosis of patients with oral cancer, only one study showed that Notch1 immunoexpression was associated with worse overall survival." (PMID 33854547, 2021). "Previous studies regarding the immunoexpression of CSC markers, ALDH1 and Notch1, have investigated the associations with clinicopathological variables and/or with the prognosis of patients with oral cancer according to the immunostaining pattern of expression." (PMID 33854547, 2021). "Clinical strategies for personalized care in oral carcinoma patients can be advanced through the combined execution of NOTCH1-targeted intervention techniques with precision-based surgeries." (PMID 40672020, 2025). "Determining the function of NOTCH1 requires comprehensive functional research to explain the precise mechanisms through which it regulates immune responses in oral cancer." (PMID 40672020, 2025). "Research data demonstrated that substantial NOTCH1 protein overexpression occurred consistently in oral carcinomas, specifically in OSCC and MEC cases." (PMID 40672020, 2025). "The investigation results show that NOTCH1 exhibits substantial elevation during oral cancer development, particularly in cases of OSCC, and is associated with tumor progression." (PMID 40672020, 2025). "The investigation indicated that NOTCH1 stood as an effective biomarker and therapeutic target for oral cancer." (PMID 40672020, 2025). "Collaborative studies have substantially contributed to the understanding of NOTCH1 expression in different oral cancer types, since this knowledge helps in guiding how patients are treated." (PMID 40672020, 2025). "With increased NOTCH1 expression in oral cancer tumors, the efficacy of surgical treatment decreases." (PMID 40672020, 2025). "Future research must assess the therapeutic value of NOTCH1 inhibitory treatments for oral cancer through time-based clinical trials." (PMID 40672020, 2025). "The experimental data showed that NOTCH1 regulates the immune response, which subsequently promotes oral cancer development." (PMID 40672020, 2025). "To better understand the role of the Notch pathway in oral cancer, we first analyzed for NOTCH-1 expression by immunohistochemical staining." (PMID 37859809, 2023). "In this study, NOTCH1 was aberrantly expressed in human oral cancer tissues compared with that in normal marginal tissues and was associated with poor prognosis." (PMID 37859809, 2023).
oral cancer (continued). "Correlations between Notch1 expression and the clinicopathological characteristics of patients with oral cancer were investigated." (PMID 37859809, 2023). "To explore the potential application of determination of Notch1 levels for early diagnosis and prognosis in oral cancer, we analyzed the correlation between Notch1 expression and patient clinicopathological features and survival." (PMID 37859809, 2023). "This study aimed to explores the expression of NOTCH1 in oral cancer tissues and its influence on prognosis." (PMID 37859809, 2023). "NOTCH1 is physiologically expressed in the basal cells of the oral squamous epithelium and its expression is inhibited in oral cancer and oral epithelial dysplasia." (PMID 37008245, 2023). "In the present study, immunohistochemical (IHC) analysis was used to examine the protein expression of NOTCH1 in oral cancer patients." (PMID 37859809, 2023). "In this present study Notch1 expression was seen in the cytoplasm of oral cancer cells, while a weak expression was found in normal tissues 4, 31-33." (PMID 37859809, 2023). "In conclusion, high NOTCH1 expression is observed in oral cancer and more likely to worsen survival in poorly differentiated oral cancer patients." (PMID 37859809, 2023). "Immunohistochemical examination revealed that Notch1 was accumulated in the cytoplasm or nuclei of human oral cancer samples." (PMID 37859809, 2023). "Based on bioinformatic studies and evaluations of Oral Squamous Cell Carcinoma (OSCC) data sets, the receptor Notch1 was the 4th highest protein of interest involved in oral cancer." (PMID 30917608, 2019). "The immune escape induced by NOTCH1 could be the reason behind resistance to therapy and worse outcomes in oral cancer patients." (PMID 40672020, 2025). "Moreover, in order to clarify the exact role of NOTCH1 in the development of oral cancer, it was necessary to explore its influence on the function of the immune system." (PMID 40672020, 2025). "The research indicates that NOTCH1 is a critical biomarker in oral carcinoma pathophysiology." (PMID 40672020, 2025). "If NOTCH1 biomarkers are accurately assessed for diverse clinical traits, including immunological responses and patterns of therapeutic reaction, there can be advances in personalized treatments for oral cancer as part of precision medicine." (PMID 40672020, 2025). "The study also aimed to examine the correlation between NOTCH1 expression and clinical staging, with the goal of determining whether NOTCH1 could serve as a prognostic biomarker and potential therapeutic target in oral cancer." (PMID 40672020, 2025). "Given the role of the Notch1 pathway in drug resistance in oral cancer, this signalling pathway may offer an important potential target for preventing chemoresistance to cancer therapy." (PMID 41228271, 2025). "Studies have indicated that disordered NOTCH1 expression causally links the immune system, tumour spread, and causes a negative impact on cancer therapy in carcinomas, especially oral cancers." (PMID 40672020, 2025). "In the clinical setting of the sample, the NOTCH1 mutation seems to be not very frequent, although NOTCH1 has been described as a gene related to oral cancer in other geographical settings." (PMID 37008245, 2023). "Our result clearly demonstrates the oncogenic role of Notch1 in oral cancer and Notch1 may be a useful biomarker to target oral cancer patients." (PMID 37859809, 2023). "It has been described that the average mutational rate for Notch1 in oral cancer was 12.67% compared to 4% for Notch2 and Notch3." (PMID 35047986, 2020).
oral cancer (continued). "Our observations on mtDNA mutations in oral cancer were similar to those made by a study on nuclear DNA mutations in paired benign and cancerous OSCC tissue samples: Izumchenko and colleagues reported that NOTCH1 mutations were found in 54% of primary OSCC and 60% of pre-malignant lesions." (PMID 26262956, 2015). "We report the molecular docking analysis data for oral cancer drug, cetuximab with NOTCH signaling pathway targets such as NOTCH1, NICD and HES1 which regulates Epithelial Mesenchymal Transition (EMT)." (PMID 37822809, 2023). "However, the authors of the study concluded that NOTCH1 expression did not influence the prognosis of patients with oral cancer, the results of other authors, although it appears to contribute to the identification of patients with OSCC." (PMID 37008245, 2023).